CD4 (CD4 molecule)
Diseases named in the same sentence as CD4 in open-access papers (continued):
Sharing a sentence is not in itself a finding about the gene and the disease.
infection (continued). "During the course of infection, the HIV-1 envelope must adapt to facilitate replication despite a decrease in its preferred CD4+ target cell population." (PMID 28264054, 2017). "Moreover, at least in vitro macrophage-based transmission of infection to CD4+ T cells (and vice versa) can be resistant to antiretroviral therapy and to some BNAbs, suggesting that current therapies may be insufficient or inadequate to stop cell-to-cell spread of the virus." (PMID 28752134, 2017). "CD4+ T cells and several cytokines, such as the Th1 cytokine IFN-γ, are critical in the control of this infection." (PMID 28584007, 2017). "The adaptive immune response includes a strong CD4+ and CD8+ T-cell response, as well as the production of neutralizing antibodies that begins during the acute phase of infection." (PMID 29255464, 2017). "To further study the cytokine pattern of pulmonary CD4+ T-cell populations, we compared HDM allergic mice with those that additionally contracted an infection." (PMID 29184554, 2017). "During the acute phase of infection, we observed an increased expression of GRAIL with low Otub-1 and mTOR expression and activation in CD4 T cells." (PMID 28114324, 2017). "Further, and virtually all of the antigen-experienced TCR transgenic CD4+ and CD8+ T cells responding to infection were identified using the surrogate marker approach." (PMID 28231312, 2017). "From 2 to 10 weeks of infection, increased frequencies of IFN-γ+ and IL-17+ CD4+ T cells were seen in the lungs of WT mice when compared with Nlrp3−/−, Casp1/11−/−, and Asc−/− mice." (PMID 28740491, 2017). "Along with CD4+ T lymphocytes, macrophage lineage cells play key roles in HIV-1 pathogenesis throughout the course of infection." (PMID 28661459, 2017). "The proportions of CD4+ T cells that expressed ROR-γt, IL-17 or IFN-γ were low in MLN of both genotypes after infection." (PMID 28968468, 2017). "We recently reported that CD4, CXCR4, and CCR5, when coexpressed simultaneously, form trimeric complexes that block HIV-1 binding and infection." (PMID 28360196, 2017). "We identified the effector memory CD4+ T cell subpopulation as the main subset of cells expressing HIV during both untreated and treated infections." (PMID 28698276, 2017). "In contrast, DCs from TLR2−/− mice infected with L. braziliensis were more competent in priming naïve CD4+ T cells in vitro, promoting in vivo increases in IFN-γ production and resistance to infection." (PMID 28280488, 2017). "In the liver, at the early stage of infection (4 DPI), only chickens of group IC showed a significant increase of CD4+ T cells." (PMID 28662952, 2017). "Recent research in immunity to leishmaniasis disclosed the importance of multifunctional CD4+ and CD8+ T cells in the generation of a Th1 response to control infection." (PMID 28280494, 2017). "Animal and human studies of intracellular pathogens have extensively evaluated polyfunctional CD4+ T cells producing multiple pro-inflammatory cytokines (IFN-γ, TNF-α, and IL-2) as a possible correlate of protection from infection and disease." (PMID 29051764, 2017). "In general, IL-7Rneg CD4+ and CD8+ T cells exhibited a much more activated phenotype than IL-7Rpos cells one month after infection, as shown by the elevated expression of Ki67, indicating recent proliferation, and HLA-DR, indicating cell activation." (PMID 29112951, 2017). "The number of IFN-γ-expressing macrophages present in POP2 mice at day 6 in our infection model is substantial, while the number of IFN-γ+ CD4 and CD8 T cells, NK cells and γδT cells are low." (PMID 28580947, 2017). "During the course of infection, these TH1-type CD4+ T cells acquire a cytotoxic profile, lose CD27 and CD28, and obtain granzyme B." (PMID 28392788, 2017). "During infection, CD8+ T cells in perigonadal fat expressed an effector phenotype (CD8+ CD44– CD69+) that was also seen in the lung where, in addition, CD4+ T cells with similar characteristics were identified." (PMID 29040326, 2017).
infection (continued). "To describe the effect of the diffusion coefficient DIFN on the T-cells production, we compared the cumulative numbers of CD4 + and CD8 + T cells as well as the infection load over the overall time of the simulation for the two scenarios." (PMID 28681703, 2017). "The results of these flow-cytometric experiments showed a relatively even expansion of CD4 and CD8 cells in each of the vaccinated groups over 70 days of the infection." (PMID 29046306, 2017). "Several T cell subpopulations which exert cytotoxic functions, such as CTLs (CD3+CD4-CD8+) and Th/memory (CD3+CD4+CD8+), were significantly higher after HV-PRRSV infection when compared with NADC-20 infection." (PMID 28839507, 2017). "Early during infection, human CMV (hCMV)-specific CD4+ T cells were demonstrated to produce IFNγ and exhibit a TH1 phenotype." (PMID 28392788, 2017). "Treatment with rapamycin on day 4 translated into an increase in total splenocytes, as well as an increase in total lymphocytes, including both CD4+ and CD8+ T cells, by day 6 post-infection." (PMID 29121917, 2017). "Vaccination of mice with BCG ΔureC::hly induced more CD4+ central memory T cells (TCM) than BCG vaccination, which were protective against infection." (PMID 29312295, 2017). "Despite their overall very low percentages, CD4+/IFN-γ+ T-cells were increased on days 61 (p<0.05) and 150 pi (p<0.01) compared to the pre-infection time point." (PMID 28045974, 2017). "Following activation for 24hr, purified blood CD4+ T cells were treated with TFV (0.33–3277 μM) or TAF (0.01–10,000 nM) for another 24hr prior to extensive washout and infection with BaL (MOI 0.1) as described in Methods." (PMID 29255206, 2017). "The resulting transgenic HIV-1 effector cells mixed with Raji/CD4-Tag-BFP target cells will quantitatively measure the cell synapse formation and the level of cell coculture infection in one step using multicolor flow cytometry analysis." (PMID 29099045, 2017). "In the NHP model, both CD4+ and CD8+ T cells were expanded as plasma viral RNA loads decreased following infection of rhesus macaques with an Asian lineage ZIKV strain." (PMID 28608813, 2017). "We first probed infection on TZM-bl, which were previously estimated to carry 4x105 CD4 and 1.3x104 CCR5 receptors per cell, and stimulated PBMC which were estimated to express a pre-activation average of 6x103 CD4 and 593 CCR5 receptors per cell." (PMID 28264054, 2017). "In general, CD4+ type 1T helper cells and CD8+ cytotoxic T cells are the major producer of IFN-γ during infections." (PMID 28936213, 2017). "Using CD11c-Cre mediated RFP fate mapping, we in fact observed that ∼25% of colonic CD4+ T cells, as well as a minor fraction of ILC3 (∼10%) were RFP-labelled upon infection with C. rodentium." (PMID 28520792, 2017). "Surprisingly, CXCL14 had a similar enhancement effect on infection by R5-tropic HIV-1, which requires CCR5 as a coreceptor for entry into CD4+ target cells." (PMID 28360196, 2017). "Consistently, activated CD4+ and CD8+ T cells (CCR7−CD45RA) were observed in the spleen of 8 out of 12 animals over the course of infection." (PMID 28290449, 2017). "We found that the infection led to an increase in the expression of PD-1 and CTLA-4 in spleen CD4 T cells from infected mice at 21 days p.i. compared to control cells." (PMID 28114324, 2017). "To further assess the potential effects of AH23848 treatment on the responses of IFN-γ-producing CD4+ and CD8+ T cells in the CNS, we analyzed intracellular IFN-γ production by the T cells 8–9 days post-infection." (PMID 28445497, 2017). "Not only do local inflammatory signals enhance dendritic cell migration and increase trans infection of T-cells, but immune activation also increases both the number and HIV-permissiveness of genital CD4 T-cells." (PMID 28893286, 2017). "CDM33 also inhibited HIV-1 cell-cell fusion and infection of cells expressing CD4 and either the CCR5 or CXCR4 co-receptors at similar concentrations to CD4." (PMID 28074089, 2017).
infection (continued). "To address this, we infected B7-H1KO mice intracranially with TMEV-OVA8 and treated mice with control IgG or anti-PD-1 antibody on day 3 post-infection and assessed the distribution of CD8+ and CD4+ T-cells in the CNS and spleen." (PMID 29170671, 2017). "Low frequency SI specific IFNγ producing CD4 and CD8 cells were detected in the lungs four days post-infection, reaching a peak at nine days post infection." (PMID 28475122, 2017). "The frequency of CD4+ T-cells expressing IFN-γ in both cultures increased over the 96h course of infection and this frequency was only slightly lower in the LAG-3 silenced CD4+ T-cells in comparison to the control co-cultures sans LAG-3 silencing." (PMID 28880895, 2017). "We have further studied the expression of intracellular pro-IL-1β, IFN-γ, IL-4, IL-17, and TGF-β cytokines by CD4+ and CD8+ T cells in the lungs of infected WT, Nlrp3−/−, Casp1/11−/−, and ASC−/− mice at 48 h, 2, 4, and 10 weeks of infection." (PMID 28740491, 2017). "In wild-type mice, EV-A71 infection increased the numbers of CD19+ B cells, CD4+ T cells, and CD8+ T cells with a significant difference found in the number of CD4+ T cells (P < 0.05)." (PMID 29233145, 2017). "Additionally, phagocytosis of opsonized virions may itself reduce the probability of successful infection of tissue resident CD4+ T cells, the primary targets of mucosal infection in humans and macaques, by reducing the half-life of infectious virus (23, –, 25)." (PMID 27795431, 2017). "Effector CD4+ T cells express the highest level of CCR5 and are depleted drastically early after infection in what is known as the acute phase." (PMID 29259605, 2017). "Third, protein aggregate-based immunization results in balanced expansion of memory CD4+ and CD8+ T cells that elicit immediate effector functions in response to challenge with pathogen infection." (PMID 29230211, 2017). "Median CD4+ at the last visit was 164 (IQR: 80–390), and median estimated duration of infection was 14 years (IQR: 10–19)." (PMID 28953320, 2017). "Infection with CH040.c resulted in detectable CD4+ T cell depletion relative to mock-infected cells in 90% of LPMC donors, whereas CH058.c and CH470 depleted CD4+ T cells in 60% of LPMC donors by 6 dpi." (PMID 28241075, 2017). "The frequency of CD4+ T cells expressing both LAG3 and CD49b (Tr1 cells) increased with infection and was further enhanced by bpV(phen) treatment." (PMID 28710387, 2017). "TC_0037 and C. muridarum-specific IFN-γ+ CD4+ and CD8+ T cell responses were assessed by ELISPOT 2 weeks after final immunization or infection." (PMID 28459057, 2017). "In conclusion, single-cell RNA-seq allowed the investigation of CD4+ T-cell heterogeneity prior to infection and led to the identification of markers for permissiveness to HIV cellular infection." (PMID 29073251, 2017). "Similar to results obtained for CD4+ T cells, the frequency of CD8+ T cells was induced 6 h after infection." (PMID 28883509, 2017). "During infection, 11% of total CD4+ T cells in MLN of B6 mice were GATA3+ while 12% of total CD4+ T cells expressed Foxp3 in infected Irf8-/- mice." (PMID 28968468, 2017). "In TLR7−/− mice, JEV infection induced higher levels of pDC and improved the responses of JEV-specific CD4+ and CD8+ T cells involved in viral clearance during the early and late phases of infection, respectively." (PMID 28265274, 2017). "In the present work we detect a clear overlap between the CD4+ and CD8+ T cell responses triggered after recombinant Ad5 vaccination and PPRV experimental infections." (PMID 29157291, 2017). "Peripheral blood CD4+CD25+ and CD4+CD25− T cells were harvested from FIV− control cats and chronically infected (between 6 months and 12 months post infection) FIV+ cats." (PMID 29056671, 2017). "Five weeks post-infection, HIV-1 disseminated into systemic tissues, in a dose-dependent manner, followed by depletion of hCD45+ CD3+ CD4+ cells." (PMID 29127409, 2017).
infection (continued). "Overall, these results reveal that vaccination with full-length N123, N23, or N1 in combination with the adjuvant CpG increased IFN-γ and IL-17 production by both CD4+ and CD8+ T cells at the site of infection." (PMID 28947645, 2017). "This migration pattern of Tcm was theorized based on our data of CD4 IFN-γ+ T cell migration to and from iLN during MoPn infection." (PMID 28106821, 2017). "This protective inflammatory response was composed of increased numbers of PMN leukocytes and activated CD4+ and CD8+ T lymphocytes that migrate to the site of infection." (PMID 28740491, 2017). "It has been shown that CD4, along with CCR5 and CXCR4, acts as the receptor for virus entry, which allows not only for the infection of CD4 T cells but also antigen-presenting cells such as macrophages and DCs." (PMID 28220120, 2017). "Using an intravenous (i.v.)disseminated infection mouse model, we observed that more CD8+ T cells than CD4+ T cells were present in the spleen of infected mice at 12 dpi." (PMID 28723951, 2017). "The results presented so far show that both CD4+ and CD8+ T cells can mediate protection against R. typhi in this model of infection." (PMID 28222146, 2017). "Although CD4+ T cells are a major adaptive source of IFN-gamma, their ability to respond to infection is slower than that of NK cells." (PMID 28488245, 2017). "SupT1 CD4+ T cells were infected with HIV-1 and aliquots of the infected culture were taken at different time points post infection." (PMID 29021215, 2017). "Similar to the CD4+ T cell proliferative response, Ki67+CD8+ T cell subsets from both SVIR001- and SVIR002-treated animals increased throughout infection and the maximal level was observed at 7 dpi." (PMID 28628616, 2017). "CsA treatment inhibits HIV-1 replication in some T cell lines and primary CD4+ T cells, suggesting that CypA binding evolved to facilitate HIV-1 replication in its natural target cells of infection." (PMID 28827840, 2017). "Perforin expression remained higher in CD4+ and CD8+ T cells of subjects with remote infection compared to expression in seronegative subjects." (PMID 29112951, 2017). "Conditional deletion of Blimp-1 in CD4+ T cells regained CD8+ T cell function and improved infection control." (PMID 28629373, 2017). "CD4+ T cells producing IFN-γ in response to MeV peptide stimulation were most abundant in circulation at 10 and 84 days after infection." (PMID 28904342, 2017). "We used this model to explore the dynamics of the CD4 and CD8 T cell responses upon primary infection, both at the site of infection (i.e. lung) and the draining mediastinal lymph node (MLN)." (PMID 28615708, 2017). "In the co-culture model where CD4+ T-cells were isolated from lungs of Mtb-infected animals, the frequency of IFN-γ positive T-cells appeared to be lower at 24 and 48h post-infection in the LAG-3 silenced co-culture in comparison to the untreated culture." (PMID 28880895, 2017). "In wild-type mice, EV-A71 infection slightly increased the numbers of CD19+ B cells, CD4+ T cells, and CD8+ T cells." (PMID 29233145, 2017). "What determines the resolution of infection in only 20% HCV infected patients is not clearly understood but is thought to be explained by an effective anti-viral CD8+ and CD4+ T cell response." (PMID 28421070, 2017). "As an additional test for the requirement for CD4 T cell help in the generation of bone marrow IgM plasmablasts, mice were administered a CD40L-blocking antibody (MR-1), on days 8, 10, and 12 post-infection." (PMID 28575114, 2017). "Kinetic studies during infection demonstrated differences in sensitivity of thymic subpopulations: Immature single positive (ISP) > DP1, DP2 > DN3, DN4 > DN2 > CD4+ > CD8+." (PMID 28091621, 2017). "Another remarkable finding is that the decrease in both CD4+ and CD8+ SPs thymocyte numbers was observed at 21 and 35 days post-infection, much later than the decrease in DP (13 d.p.i.)." (PMID 28147332, 2017).
infection (continued). "At day 4 post infection, HEL-specific CD4+ T cells from sTg-IRBP:HEL mice and nTg controls displayed comparable levels of PD-1 and numbers of HEL-specific CD4+ Foxp3+ Treg were equivalent in these mice." (PMID 29079770, 2017). "IFN-γ secreting lung CD4 T cells induced by M2e5x VLP vaccination and virus challenge were observed at a higher level compared with that in naïve mice after infection." (PMID 29276514, 2017). "These kinetics of CD4+ and CD8+ T cells resulted in an increased CD4+/CD8+ ratio during the course of infection." (PMID 27799331, 2017). "We determined the percentage of CD11a+CD49d+ CD4+ T cells and CD8αloCD11ahi CD8+ T cells at baseline (day -1) and at the peak of the T cell response, 8 days post-infection (dpi)." (PMID 28231312, 2017). "The peritoneal fluid from both vaccinated and challenge control rats contained significantly fewer CD4+ and CD8+ cells than the peritoneal fluid from uninfected control rats on day 35 post-infection." (PMID 28333957, 2017). "DT-treated WT and CD169-DTR mice were infected with RSV, and CD44hi CD62Llo CD4+ and CD44hi CD62Llo CD8+ T cells were assessed by flow cytometry on day 7 after infection." (PMID 28751894, 2017). "In 3 of these trials, infection and/or poor control of viremia directly correlated with the induction of vaccine-specific IFN-γ+ CCR5+ CD4+ T cells in blood (22; Amara, personal communication)." (PMID 29021394, 2017). "Strong associations were observed among most markers of immunosenescence and disease progression, especially between the naïve CD4+ T cell count and the CD4+ T cell count (r = 0.79) or CD4/CD8 ratio (r = 0.60, P < 0.0001 for all) during infection." (PMID 28232735, 2017). "Infection of hu mice with HIV strains, such as the CXCR4-tropic strain NL4-3, usually results in progressive CD4+ T cell depletion similarly to HIV-infected individuals." (PMID 28558649, 2017). "In the early stages of infection, HIV preferentially infects and depletes CCR5-expressing CD4+ T-cells in the gastrointestinal tract (GIT)." (PMID 29209103, 2017). "The numbers of CD4+CD25+Foxp3+ T cells were similar in naïve B6 and Irf8-/- mice, but this population expanded early during infection in both B6 and Irf8-/- mice." (PMID 28968468, 2017). "Although repeated infections slightly increased CD8+ T cell numbers (D42pi and D70pi), CD4:CD8 T cell ratios were unchanged as CD4+ T cell numbers slightly increased concomitantly." (PMID 28662714, 2017). "This pattern of reactivity was maintained in the late stages of infection, although frequencies of HCMV-specific CD4+ and CD8+ T cells (particularly IE-1- and pp65-specific) decreased." (PMID 29112951, 2017). "For this purpose, we analyzed the changes in expression of multiple activation/exhaustion markers on the surface of CD4+ and CD8+ T cells in our different cohorts during infection (day 5 postinfection)." (PMID 28811340, 2017). "During infection with T. brucei rhodesiense in a mouse model, a subset of VSG-specific TCRαβ+ CD4+, but CD8−, T cells has been shown to secrete high levels of IFN-γ." (PMID 28936213, 2017). "Infection with both HIV BaL and HIV IIIB strains showed decreased mRNA levels of CD4 and their corresponding co-receptors." (PMID 28060951, 2017). "Of note, in the SIV-NHP model of infection, T cell vaccines delivering SIV proteins can elicit cellular immune responses, reduce viral loads, and preserve memory CD4 T cell numbers." (PMID 28893280, 2017). "During chronic phase of infections when CD8+ T cells often become functionally exhausted, the CD4+ T cells appear to take over some of the direct antiviral activities of CD8+ T cells." (PMID 28798348, 2017). "An efficient antiviral response induces the recruitment of RSV-specific CD4+ and CD8+ T cells to the infection site by the CXCL9 and CXCL10 chemokines, which are induced by IFNs and the chemokine receptor CXCR3." (PMID 28751894, 2017).